MTOR (mechanistic target of rapamycin kinase)
Diseases named in the same sentence as MTOR in open-access papers (continued):
Sharing a sentence is not in itself a finding about the gene and the disease.
tumor (continued). "Although tumors present a shortage of nutrients due to their underdeveloped vasculature, mTOR is overactivated in most human tumors and promotes tumor growth, proliferation, and metastasis." (PMID 35163745, 2022). "Meanwhile, there are also a number of clinical studies demonstrating adjuvant effects of mTOR inhibitors on tumor recurrence." (PMID 35681642, 2022). "Treatment with an mTOR inhibitor (i.e., everolimus) led to tumour shrinkage and disease stabilisation in patients with NSCLC." (PMID 36577970, 2022). "Proximity in the perivascular tier determined a distinctive mammalian target of rapamycin (mTOR)-derived anabolic metabolism in the tumor cell, which resulted in increased aggressiveness and resistance to chemo- and radiotherapy." (PMID 35740307, 2022). "A previous study of 528 HCCs evaluated by immunohistochemistry demonstrated that enhanced PI3K/AKT/mTOR signaling was correlated with poor tumor differentiation, higher TNM stage, and vascular invasion." (PMID 35174643, 2022). "Together, our data consistently demonstrated the PI3K/AKT/mTOR pathway played a pivotal role in translating tumor-derived signals into Bcl6-mediated SMMs differentiation program." (PMID 36542153, 2022). "A relevant research has shown that the activation of Akt/mTOR signalling pathway is vital to tumour development, progression and prognosis in ESCC cells." (PMID 35315581, 2022). "The phosphoinositide 3 kinase (PI3K)/Akt/mammalian target of rapamycin (mTOR) pathway is a complicated signalling pathway involved in tumour growth and proliferation." (PMID 35954393, 2022). "After using mTOR inhibitors, for example, resistance occurs because of the activation of other tumor-related pathway elements and downstream of mTOR." (PMID 36313041, 2022). "The mTOR pathway is undoubtedly extremely important for cell proliferation, survival, and metabolism, and can play a critical role in tumor initiation and progression, therapy resistance, and poor outcomes." (PMID 35326708, 2022). "In this study, we confirmed that miR-99b-5p functions as a tumor suppressive miRNA, and its expression contributes to the suppression of MTOR expression at transcriptional and translational levels in PCa." (PMID 35328346, 2022). "The Akt-mTOR pathway is generally considered to play a role in the proliferation of tumor cells and is involved in progestin resistance." (PMID 36293372, 2022). "In general, most tumours have their own mutation profiles, and few genes are commonly found in all tumours although, like most other carcinomas, ERBB2/PI3K/AKT/mTOR are most affected." (PMID 35725812, 2022). "HIF‐1α and/or Glut‐1 knockout also abrogated PI3K/Akt/mTOR signalling transduction in tumour tissues, in a manner similar to wortmannin." (PMID 35415942, 2022). "In CRC, forward ephrin-B signaling is a tumor suppressor pathway, whereas Wnt and mTOR are two oncogenic pathways." (PMID 35780836, 2022). "The abnormal activation of mTOR signaling pathway is considered to be one of the key signaling pathways regulating tumor metabolism." (PMID 35022030, 2022). "This pharmacokinetic characteristic is critical because it can effectively block mTORC1 and two and PI3K signal transduction in tumour tissues (VS-5584 with mTOR and PI3Kα activities of 37 and 16 nM, respectively)." (PMID 35614940, 2022). "The PI3K/AKT/mTOR pathway can prevent programmed death of tumor cells and inhibit apoptosis, thus promoting the survival of tumor cells." (PMID 35311154, 2022). "The suppression of ATF6 or the Ras homolog enriched in brain (Rheb) reinstates rapamycin resistance in dormant tumor cells, revealing the regulation of autophagy in tumor cells via the ATF6-Rheb-mTOR pathway." (PMID 36497032, 2022). "The mTOR inhibitor everolimus has demonstrated antitumoral activity, including the inhibition of tumor proliferation and angiogenesis." (PMID 36556296, 2022).
tumor (continued). "In NK cells, increased ROS can consistently activate the mTOR/Drp1 pathway, leading to mitochondrial fission and subsequent apoptosis, thereby inhibiting NK cell activity and tumor-killing capacity." (PMID 36424540, 2022). "Taken these data together, it suggested that SLC6A14 regulated the activity of Akt-mTOR signaling molecules, which is a key pathway in the control of tumor cell proliferation and mobility." (PMID 35907820, 2022). "We demonstrated that dual targeting of AKT and mTOR has a synergistic effect on the inhibition of HCC cell proliferation in vitro as well as on tumor growth and survival in a subcutaneous xenotransplantation mouse model in vivo." (PMID 35454789, 2022). "Nevertheless, in malignant tumor cells, an abnormally phosphorylated mTOR promotes uncontrolled tumor cell growth, invasion of nearby tissues, and metastasis." (PMID 36079025, 2022). "The PI3K/Akt/mTOR signaling pathway is involved in several biological processes such as cell survival, apoptosis, and tumor development and progression." (PMID 35359411, 2022). "PI3K/AKT/mTOR pathway activation is closely related to PD-L1 expression and impacts the tumor immune microenvironment." (PMID 36313041, 2022). "Fat cells secrete inflammatory growth factors and cytokines; among these, leptin and interleukin 6 (IL-6) play roles in the activation of the mTOR signaling pathway and are involved in tumor progression and resistance to chemotherapy treatments." (PMID 35805003, 2022). "Inhibition of CASC9 upregulates the phosphorylation level of AMPK and suppresses Akt-mTOR signaling, inhibiting tumor growth and inducing autophagy in HCT116 and SW480 human CRC cells, which is a promising strategy for CRC therapy." (PMID 36172152, 2022). "Nonetheless, carbonic anhydrase IX (CAIX), overexpressed on membranes of hypoxia tumor cells with pH-regulatory effects, attenuates intracellular acidity, which is unfavorable for mTOR inhibition." (PMID 35413842, 2022). "The knockdown of TIM3 alters a variety of pathways, including AKT, P13K, mTOR, and NF-κB, which are all downregulated, resulting in the inhibition of tumor proliferation and increased apoptosis." (PMID 36358792, 2022). "Compared with the LPS group, the degree of tumor apoptosis in the LPS+mTOR inhibitor+matrine group was significantly increased (P < 0.05)." (PMID 35400284, 2022). "Here, we demonstrate that our original diet prevented tumour growth by inhibiting mTOR activity and stimulating ER stress." (PMID 35367410, 2022). "The PI3K/AKT/mTOR signaling pathway is dysregulated in nearly all kinds of neoplasms, with the component in this pathway alternations." (PMID 36539659, 2022). "Cluster 1 was enriched for “cell cycle,” “DNA repair”, and “mTOR signaling”, which facilitated tumor initiation, survival, and exacerbation." (PMID 35646893, 2022). "Many studies have reported that magnolol inhibited tumor cell proliferation through attenuating the PI3K/Akt/mTOR signaling." (PMID 36234977, 2022). "Increasing evidence has shown that the mTOR pathway is important for tumour progression and therapy." (PMID 36294896, 2022). "Through the regulation of many cellular and molecular functions, the AKT/mTOR signaling pathway is essential for tumor initiation, invasion, and metastasis and plays a key role in the development of CC." (PMID 36471885, 2022). "Recently, the protein kinase B (AKT)/mammalian target of rapamycin (mTOR) signal pathway is over-activated in numerous tumors, including NSCLC, and associated with tumor angiogenesis, invasion, metastasis and so on." (PMID 35596155, 2022). "Previous studies have reported that the mechanisms of the anti-tumor activity of quercetin include the modulation of the PI3K/Akt/mTOR, Wnt/-catenin, and MAPK/ERK1/2 pathways." (PMID 35571106, 2022). "Pre-treatment with thymoquinone led to marked suppression in p-AKT, p-mTOR, and p-S6 in tumor tissues of xenografted mice." (PMID 35682990, 2022).
tumor (continued). "By phosphorylating AMPK and other substrates, LKB1 is regarded as a major tumour suppressor and regulator of metabolism that acts mainly by inhibiting the mammalian target-of-rapamycin (mTOR) pathway." (PMID 36433955, 2022). "The aberrant regulation or hyperactivation of mTOR is a distinctive sign of many tumours, including haematological malignancies." (PMID 36009482, 2022). "Evidence shows that the PI3K/AKT/mTOR pathway has a significant role in tumor initiation and development and mediates the EMT process." (PMID 35954442, 2022). "In this sense, the genetic and pharmacological inhibition of PI3K/mTOR signaling induces a reduction of tumor hypoxia." (PMID 35565420, 2022). "Activation of the mTOR signaling pathway is correlated with metabolic activity, increased cell proliferation, and support of tumor survival." (PMID 36430245, 2022). "As a central signaling pathway controlling tumor metabolism, mTOR signaling pathway is one of the signaling pathways deeply studied in tumor." (PMID 35022030, 2022). "It was found that sinomenine can inhibit growth and invasion through the MAPK/ERK and PI3K/Akt/mTOR pathways in multiple tumor cells." (PMID 36142613, 2022). "Reintroduction of CCT4 or mLST8 expression in YB-1–knockdown GSCWL1 and GSC456 cells reactivated mTOR signaling and partially rescued cell proliferation, tumor-sphere formation, and GSC self-renewal." (PMID 35239512, 2022). "The PI3K/AKT/mTOR pathway is involved in tumor formation, cell cycle progression, cell cycle progression, survival, and even apoptosis." (PMID 35647006, 2022). "Other studies also support our findings, as these studies reported that the inhibition of mTOR signalling facilitates the adaptation of tumour cells to unfavourable conditions." (PMID 36433955, 2022). "A novel connection between CD49f (integrin α6) and the PI3K/AKT/mTOR signaling pathway in tumor cells has been identified." (PMID 36033461, 2022). "Activation of the PI3K/Akt/mTOR pathway mediated by molecular aberrations plays a crucial role in promoting tumour development and resistance to anticancer therapies." (PMID 35614940, 2022). "Restricting essential amino acids uptake into the tumor cell suppresses its proliferation via inhibition of mammalian target of rapamycin (mTOR)-p70S6 Kinase (p70S6K) pathway." (PMID 35046465, 2022). "The activation of PI3K/Akt/mTOR pathway in cancers leads to rapid proliferation, apoptosis escape and chemoresistance of tumour cells." (PMID 35106915, 2022). "Our research also revealed that ATRAP contributes to activation of the AKT/mTOR pathway, leading to tumor progression." (PMID 35414770, 2022). "The PI3K/Akt/mTOR signaling pathway is an important signal transduction system that can affect the growth, proliferation, survival, metabolism, and angiogenesis of tumor cells." (PMID 35463631, 2022). "The tumor suppressor gene PTEN, a negative regulator of the PI3K/AKT/mTOR pathway, is mutated and lost in up to 80% of UCEC tumors." (PMID 36163440, 2022). "Activation of the PI3K/AKT/mTOR pathway in tumor cells can also increase VEGF secretion, both by hypoxia-inducible factor 1 dependent and independent mechanisms." (PMID 35903690, 2022). "TIPRL also promoted AMP-activated protein kinase (AMPK) activation, which in turn reduced phosphorylation of mTOR, 4EBP-1, and S6K, resulting in mTOR signaling deactivation and consequent inhibition of tumor invasion in GC." (PMID 36212146, 2022). "As a serine/threonine kinase, the mammalian target of rapamycin (mTOR) is considered a critical factor in tumor pathogenesis (Mossmann, Park & Hall, 2018)." (PMID 36132221, 2022). "Here, we reported that the increase of granulocyte colony-stimulating factor (G-CSF) in mouse serum with tumor progression encouraged G-MDSCs to obtain immunosuppressive traits in peripheral blood through the PI3K-Akt/mTOR pathway." (PMID 35013108, 2022).
tumor (continued). "Among the tumor-suppressive miRNAs regulating the PI3K/Akt/mTOR pathway, let-7b-5p was significantly downregulated in MM tissues and RPMI 8226 cells." (PMID 35625953, 2022). "In the present study, lower pre-neoCRT mTOR expression was observed in the tumor cell PD-L1 score 0 group." (PMID 35201501, 2022). "In conclusion, this study found that gracillin has anti-tumor effects on NSCLC, and its anti-tumor mechanism is the regulation of autophagy through the mTOR signaling pathways." (PMID 35392243, 2022). "Pharmacological inhibition of the mTOR pathway (e.g., by rapamycin or everolimus) can hamper tumor progression both in vitro and in animal models." (PMID 36344496, 2022). "Because the mTOR signaling pathway is closely related to tumor proliferation, we explored the effect of NEDD4L on its activity in LUAD cells." (PMID 35090513, 2022). "Evidence supports that IL-15 preserves stemness and induces higher anti-tumor activity and proliferation via mTOR inhibition." (PMID 36358860, 2022). "They affect cholesterol production and lipid raft integrity in tumor cells through mTOR-induced expression of adipogenic enzymes regulated by SREBPs." (PMID 36114560, 2022). "The immunohistochemistry results displayed a dramatic reduction in the degree of Ki67 and p-mTOR among LINC00857-silenced tumor tissues." (PMID 36010849, 2022). "Inhibition of PI3K/AKT/mTOR signaling pathway leads to cell cycle arrest in the G2/M phase and reduces tumor cell radio-resistance." (PMID 35875060, 2022). "Mammalian target of rapamycin (mTOR) signaling in CSCs mediates the enhancement of colony-stimulating factor (CSF) that supports MDSCs infiltration and accumulation in tumor site." (PMID 35395787, 2022). "The hamartin-tuberin complex inhibits the mammalian/mechanistic target of rapamycin (mTOR) pathways, which play a role in controlling cellular growth, cell proliferation, and suppressing tumor formation." (PMID 35359647, 2022). "On the one hand, the increase in 5-HT can stimulate the PI3K-Akt-mTOR pathway and therefore promotes tumor metabolism and thus tumor growth." (PMID 36185233, 2022). "The PI3K/AKT/mTOR pathway is also reported to participate in the immunosurveillance of the tumor microenvironment." (PMID 36313041, 2022). "Overall, our study demonstrated that LHPP function as a tumor suppressor gene in GC by regulating the PI3K/AKT/mTOR pathway." (PMID 36484014, 2022). "The AKT/mTOR pathway plays diverse roles in tumor initiation and maintenance, including involvement in the modulation of metabolic processess." (PMID 35581670, 2022). "miR-126 was shown to downregulate NFκB-mediated PI3K/AKT/mTOR signaling and PI3K inhibition has been implicated as a therapeutic target to inhibit tumor angiogenesis in multiple malignancies." (PMID 35928931, 2022). "PD-1 interacted with and promoted phosphorylation of the mTOR effectors eIF4E and S6 to enhance tumor growth." (PMID 35663968, 2022). "The previous studies have reported that CXCR4 promotes tumor progression by activating the PI3K/Akt/mTOR pathway in several types of cancer." (PMID 35681259, 2022). "Over-activation of mTOR can accelerate the cell cycle of tumor cells and promote cell migration and apoptosis-resistance." (PMID 36148953, 2022). "The HDAC inhibitor valproic acid (VPA), combined with the mTOR inhibitor temsirolimus, inhibited cell growth and triggered autophagic cell death in Burkitt’s lymphoma cell lines, primary tumor cells, and a murine xenograft model, reducing tumor growth." (PMID 36291856, 2022). "SLC1A5 is highly expressed in many cancers, including CRC, and plays an important role in supplying glutamine for energy production, autophagy, redox homeostasis, and activation of mTOR signaling, thereby promoting tumor growth." (PMID 35418865, 2022). "The results showed a synergistic action of this combination leading to a nearly total arrest of tumor growth due to the profound involvement of mTOR and EGFR activity." (PMID 36428613, 2022).
tumor (continued). "What’s more, circFTO knockdown and mTOR inhibition showed a synergistical effect on controlling the tumor growth subcutaneously." (PMID 36127345, 2022). "The differences in tumor growth at these two sites (primary and metastasis) mirrored changes in p-S6 staining, indicating that mTOR signaling was reactivated in the primary tumor but continued to be suppressed in the lung macrometastases." (PMID 35741020, 2022). "There is mounting evidence that PI3K/Akt/mTOR signaling influences key tumor progressions, including proliferation, migration, metastasis, and angiogenesis, by regulating downstream pathways." (PMID 36605098, 2022). "Most tumours contain mutations in the genes encoding kinases, including kinases that are parts of important signalling pathways such as the PI3K/Akt/mTOR pathway." (PMID 35214064, 2022). "The expression of PI3K, AKT, and mTOR was reduced in miR-383-5p-transfected BC cells, indicating that miR-383-5p acts as a tumor inhibitor by suppressing the PI3K/AKT/mTOR axis." (PMID 36313570, 2022). "The results obtained from Keap1−/− and Keap1β(Keap1Δ1–31) cells unraveled that PTEN was obviously upregulated, whilst PI3K, AKT1, and mTOR were all downregulated, showing the similar trends to those of in vivo growing tumours." (PMID 36142252, 2022). "In the tumor microenvironment, mTOR signaling regulates the activity of macrophages and T-cells through inflammatory factors like IL-10, TGF-beta, and membrane bound CTLA-4 and PD-1." (PMID 36304922, 2022). "Another drug target is the mammalian target of rapamycin (mTOR) pathway, which regulates cell proliferation and tumor metabolism." (PMID 36612261, 2022). "The activation of endothelial PI3K/AKT/mTOR pathway signals can promote the survival of cultured microtubules in vitro and tumor blood vessels in vivo." (PMID 35311154, 2022). "As a core regulator of autophagy, mTOR inhibition can initiate autophagy in tumour cells by activating the ULK1 complex and further activating the type III PI3K complex." (PMID 36042213, 2022). "Studies have shown that RAPA, as a targeted inhibitor of the mTOR pathway, exerts anti-inflammatory and anti-tumor effects in a variety of diseases by inhibiting the activation of the mToR pathway." (PMID 36405706, 2022). "Many studies have shown that the downregulation of tumor-suppressor or the upregulation of oncogenic miRs results in the activation of the mTOR pathway in HCC." (PMID 35625573, 2022). "mTOR signaling is activated in many neoplasias and therefore, lends itself as promising therapeutic target." (PMID 35814409, 2022). "A recent study found that the merge of a PI3K/mTOR inhibitor and palbociclib completely controlled tumor growth in mice." (PMID 35646104, 2022). "Activation of PI3K/Akt/mTOR cascades is a key factor in tumor cell development and survival, which ultimately advances angiogenesis, the development of metastasis, and therapeutic resistance." (PMID 36359873, 2022). "Myeloid-specific inactivation of PDK1 reprogrammed the metabolism of tumor-infiltrating macrophages and stimulated M1 macrophage polarization by inhibiting the mTOR pathway, while also retarding tumor growth and suppressing lung metastasis of BC model." (PMID 35159078, 2022). "High concentrations of K+ within tumor necrotic areas inhibit Akt/mTOR TCR signaling and T cell effector functions." (PMID 35256819, 2022). "In this regard, the hyperactivation of mTOR-downstream S6K that we found in this SCCOPT case indicates the similarity of this tumor to SCLC, suggesting that it was potentially targetable with mTOR inhibitors." (PMID 36287116, 2022).